CD27 (CD27 molecule)
Diseases named in the same sentence as CD27 in open-access papers (continued):
Sharing a sentence is not in itself a finding about the gene and the disease.
primary immunodeficiencies (7 papers, 2014 to 2025). "Prospective data collection on HSCT in ITK deficiency and other EBV prone primary immunodeficiencies, as CD27 or CD70 deficiency is highly warranted." (PMID 29867957, 2018). "For T cell subsets, we used CD45RA and CD27 to resolve the naive (CD45RA+CD27+) and central memory (CD45RAnegCD27+) stages from the effector memory (CD45RAnegCD27neg) stage, in accordance with the definition strategy used by the EuroFlow group for human primary immunodeficiency." (PMID 35222411, 2022). "An elevated proportion of IgM+IgD+CD27+ populations, together with increased VH4-34 gene usage and elevated 9G4+ staining, has been previously reported in other primary immunodeficiency diseases including Wiskott-Aldrich Syndrome." (PMID 39812873, 2025).
Alzheimer disease (6 papers, 2013 to 2025). A progressive, neurodegenerative disease characterized by loss of function and death of nerve cells in several areas of the brain leading to loss of cognitive function such as memory and language. "This network contains the proinflammatory cytokine Il1a, previously associated with Alzheimer’s disease, development and plasticity, immune associated genes (Cd80, Cr2, Cd27, Dapp1) and chemokines (Ccl3, Ccl4, Ccl21)." (PMID 23742273, 2013). "In addition, several CD20- and CD33-expressing leukocytes increased the risk of Alzheimer’s disease; CD11-expressing leukocytes increased, and CD27- and CXCR1-expressing leukocytes decreased, Parkinson’s disease risk in MR sensitivity analyses." (PMID 37118290, 2022). "As an additional supportive finding, our MR sensitivity analyses showed that several CD20- and CD33-expressing leukocytes increase the risk of Alzheimer’s disease and that CD11-expressing leukocytes may increase, and CD27- and CXCR1-expressing leukocytes may decrease, Parkinson’s disease risk." (PMID 37118290, 2022).
Arthritis (6 papers, 2014 to 2025). Inflammation of a joint. ",40Clostridioides difficile (targeted by Colneyvirus CD27) infection in collagen-induced arthritis (CIA) mice demonstrated that C. difficile infection reduced the incidence of arthritis, supporting the existence of a protective gut-joint axis." (PMID 40465264, 2025). "In this study we analysed the peripheral blood components, i.e. CD14+ monocytes, CD4+, CD8+ and CD56+T lymphocytes (CD3+), CD80+, C-X-C chemokine receptor 3 (CXCR3)+, CD27+ B lymphocytes (CD19+) and CD16+CD56+CD3− NK cells, for their association with arthritis development." (PMID 27629388, 2016). "Exploratory mass cytometry analyses reveal three circulating cellular subsets heralding the onset of arthritis flare – CD45RO+PD1hi CD4+ and CD8+ T cells, and CD27+CD86+CD21- B cells – further characterised by single-cell sequencing." (PMID 38316770, 2024). "The expression of Th senescent biomarkers, CD27, CD57, PD1, NKG2D, hTERC, or p16, in senescent Th cells from early arthritis patients was similar to those of donors, however, some of them showed an increase after 6 months of disease progression." (PMID 33291545, 2020). "We also compared axSpA patients without and with a history of peripheral manifestations including enthesitis, arthritis and dactylitis (without extra-skeletal manifestations) and observed no notable enrichment of CD27-CD38lowCD21low B-cells between groups (P=0.14)." (PMID 34168654, 2021).
co-infection (6 papers, 2011 to 2024). "HIV/HCV co-infection was associated with significantly decreased expression of the maturation/differentiation markers CD27/62L/127 on NK cells but increased expression of CD57 compared to healthy controls." (PMID 28380039, 2017). "Of note, we found HIV/HCV co-infection to be associated with a shift towards a more mature NK cell phenotype as frequency of NK cells expressing CD27, CD62L and CD127 was significantly lower than in healthy controls, whereas the proportion of mature CD57 expressing NK cells was increased." (PMID 28380039, 2017). "Compared to healthy controls we found HIV/HCV co-infection to be associated with a decreased frequency of CD56bright NK cells expressing markers characteristic for less mature NK cells, such as CD27, CD62L and CD127, whereas the proportion of CD57+ NK cells was significantly increased." (PMID 28380039, 2017). "Interestingly, in addition to HIV co-infection active TB disease was linked to further down regulation of CD27 and increased capacity of Mip-1β production in CMVpp65-specific CD4+ T cells." (PMID 25974183, 2015). "Despite the inhibitory effect that HIV infection has on T-cell differentiation, HIV-TB co-infection presents with an accelerated decline in CD27 and CD28." (PMID 38903242, 2024). "Co-infection of HIV with M. tuberculosis appears to expedite the downregulation of CD27 and CD28 compared to HIV infection alone." (PMID 38903242, 2024).
Crohn disease (6 papers, 2021 to 2024). A gastrointestinal disorder characterized by chronic inflammation involving all layers of the intestinal wall, noncaseating granulomas affecting the intestinal wall and regional lymph nodes, and transmural fibrosis. "In our study, we found that IgD− CD27− B cell counts were negatively associated with the risk of Crohn disease." (PMID 39058862, 2024). "For instance, elevated CD27 expression on memory B cell subsets is associated with an increased risk of Crohn’s disease; therapeutic targeting of CD27 on B cells may aid in reducing this risk." (PMID 38455666, 2024). "Moreover, CD27 and CD28 downregulation on CD4+ T cells has been previously associated with other intestinal inflammatory diseases such as Crohn’s Disease." (PMID 38239362, 2023).
osteosarcoma (6 papers, 2015 to 2024). A usually aggressive malignant bone-forming mesenchymal neoplasm, predominantly affecting adolescents and young adults. "In this study, expression of CD70 and CD27 was analyzed in osteosarcoma cell lines and tumor specimens." (PMID 25792975, 2015). "In this study, we sought to determine the expression of CD70 and CD27 in osteosarcoma as well as other (pediatric) solid cancers, and the correlation with clinical outcome." (PMID 25792975, 2015). "There was a negative effect of CD20 on CD24+CD27+ B cells on osteosarcoma based on the IVW (OR: 0.32 [95% CI: 0.14 to 0.72], p = 0.006)." (PMID 39081321, 2024). "The research also identified a negative association between CD20+CD24+CD27+ B cells and CD20+IgD+CD38− B cells with osteosarcoma risk." (PMID 39081321, 2024). "Our findings found that CD80 on CD62L+ myeloid dendritic cells and CD28−CD4−CD8− T-cell absolute count are positively associated with OS, and CD20 on CD24+CD27+ B cells and CD20 on IgD+ CD38 B cells have a negative effect on osteosarcoma." (PMID 39081321, 2024). "CD27, the receptor for CD70, was neither detected on tumor cells nor on T cells in CD70+ or CD70− tumors, suggesting that CD70 on tumor cells is not involved in CD27-dependent tumor-immune cell interactions in osteosarcoma." (PMID 25792975, 2015). "In contrast to CD70, its receptor CD27 was detected neither in CD70+ nor CD70− osteosarcoma lesions and was not expressed by infiltrating T cells (panel C and data not shown)." (PMID 25792975, 2015). "Moreover, CD27 was neither detected on tumor cells nor on infiltrating T cells in osteosarcoma lesions, suggesting that CD70 on tumor cells is not involved in CD27-dependent tumor-immune cell interactions." (PMID 25792975, 2015).
periodontitis (6 papers, 2019 to 2026). An acute or chronic inflammatory process that affects the tissues that surround and support the teeth. "Although this study is the first to reveal a genetic causal relationship between CD27 and periodontitis through bioinformatics and MR analyses—offering new avenues for diagnosis and treatment—it has several limitations." (PMID 41143004, 2025). "The findings indicated unique patterns of immune cell infiltration linked to the expression of the key gene CD27 in individuals with periodontitis." (PMID 41143004, 2025). "By employing the IVW method, we discovered a causal link between CD27 and the development of periodontitis (OR = 0.7536, 95%CI = 0.5886–0.9647, p = 0.02477)." (PMID 41143004, 2025). "Through the application of the inverse variance weighted (IVW) approach, our analysis revealed that the central gene CD27 is linked to periodontitis (OR = 0.7536, 95%CI = 0.5886–0.9647, p = 0.02477)." (PMID 41143004, 2025). "Significantly, it clarifies the cause‐and‐effect relationship linking the CD27 gene to the development of periodontitis, thereby presenting new possible targets for preventing and treating the disease." (PMID 41143004, 2025). "Our MR analysis confirmed a causal relationship between CD27 and periodontitis, suggesting CD27 as a potential therapeutic target." (PMID 41143004, 2025). "Our analysis of immune cell presence in periodontitis highlighted these distinct patterns linked to CD27 expression, suggesting the significant role of CD27 in regulating immune responses and its potential contribution to the progression of periodontitis." (PMID 41143004, 2025). "Our analysis established a genetic link between the CD27 gene and periodontitis, indicating its potential as a diagnostic or therapeutic target." (PMID 41143004, 2025). "OR for CD27 on switched memory B cell in relation to the risk of periodontitis, using the IVW method, was 1.066 (95% CI = 1.023–1.110, P = 2.316 × 10−3, FDR = 0.112)." (PMID 39686447, 2024). "Significantly, we explored the possible causal link between the CD27 gene and periodontitis." (PMID 41143004, 2025). "Additionally, MR analysis helps us investigate the causal relationship between CD27 and periodontitis, aiming to offer scientific evidence for future treatment strategies and new preventive and management approaches for periodontitis and its related systemic diseases." (PMID 41143004, 2025). "A systematic MR analysis that excluded each SNP one by one consistently demonstrated causal significance, suggesting that no single SNP predominantly affects the relationship between CD27 levels and periodontitis." (PMID 41143004, 2025). "In particular, we focused on examining the connection between CD27 and periodontitis." (PMID 41143004, 2025). "By generating high‐resolution three‐dimensional structures for CD27, CXCR4, and other hub proteins, AlphaFold enables the identification of key ligand‐binding interfaces—such as the CD27–CD70 interaction site—underlying immune signaling in periodontitis." (PMID 41143004, 2025). "CD27 not only acts as an immune costimulatory molecule to promote T cell activation, but its function also extends to regulating local immune imbalance and bone resorption in periodontitis." (PMID 41143004, 2025). "Multiple regression analysis revealed that besides age (p = 0.009), the double negative (CD27-IgD-) subset of CD5+ memory B cells was related to periodontitis, while total CD5+ B cell levels remained unchanged." (PMID 41708693, 2026).
pulmonary TB (6 papers, 2007 to 2022). "It is intriguing that COPD subjects had increased percentages of a different subset of lung CD4+ cells, CD62L−, CD27+ cells, which in a murine model of pulmonary tuberculosis have been linked to defective IFN-γ production." (PMID 24805101, 2014). "Smear and/or culture positive pulmonary tuberculosis can be diagnosed by a rapid and reliable immunological test based on the distribution of CD27 expression on peripheral blood tuberculin specific T-cells." (PMID 17710135, 2007). "Our results have demonstrated that CD27-expression on ex-vivo short term stimulated tuberculin specific CD4 T-cells is a highly discriminating biomarker for active pulmonary TB." (PMID 17710135, 2007). "Side-by-side evaluation of CD27- vs. CD38-based assays to distinguish active from cured TB were previously reported in a pilot study and as a case report in the context of extra-pulmonary TB." (PMID 35492319, 2022). "This work was done on blood cells rather than pulmonary lymphocytes; however, we discovered that the measurement of CD27 expression on tuberculin-reactive human CD4 T-cells is a useful and rapid tool for the diagnosis of active pulmonary tuberculosis." (PMID 17710135, 2007). "Interestingly, we also observed an increased proportion of effector memory (CD45RA-CD27-) and effector cytotoxic (CD45RA + CD27-) Vδ2 T cell subsets in HIV negative pulmonary TB patients." (PMID 30219039, 2018).
renal cell carcinoma (6 papers, 2015 to 2025). "Recently, we reported that high plasma soluble CD27 (sCD27) levels reflect the intratumoral interaction of CD70-CD27 and dysfunctional T cells in the tumor microenvironment of renal cell carcinoma." (PMID 40148586, 2025). "Furthermore, the expression of CD27, a member of the tumor necrosis factor receptor superfamily, has been associated with immune modulation in cancer, with its ligand CD70 being regulated by hypoxia-inducible factors in renal cell carcinoma." (PMID 40458414, 2025). "Unlike findings in renal cell carcinoma, we found a predominant interaction between CD27 and CD70 expressed by stromal cells compared to tumor cells, even when considering only the interaction with CD8+T cells expressing CD27." (PMID 40148586, 2025).
uveitis (6 papers, 2018 to 2026). An inflammatory process affecting a part of or the entire uvea. "This is of interest, because in young patients with early onset oligoarticular JIA (a risk factor for uveitis) switched memory (CD27+ IgM-IgD-) B cells are expanded in blood and associated with the production of anti-nuclear antibodies (ANAs)." (PMID 33042130, 2020). "Notably, although not diagnosed as Behçet's syndrome, several CD27-deficient patients also suffer from uveitis and EBV-induced oral/perianal ulcers, which are typical signs of this syndrome." (PMID 33996677, 2021). "Overall, distinct clusters of uveitis cases (termed “JIA uveitis 2”) became apparent, characterized by distinct expression of IGHD, CCR7, IGHM and CD27." (PMID 33042130, 2020). "Finally, we observed a significant decrease in CD4+ Tm CD27+CXCR5+ cells (i.e., follicular T helper cells) in uveitis patients." (PMID 30429855, 2018).
Allergy (5 papers, 2019 to 2025). An allergy is an immune response or reaction to substances that are usually not harmful. "It was found that children with allergic diseases had elevated Treg and CD27+ IgA+ B cells to compensate for chronic inflammation." (PMID 36245510, 2022). "Our results indicate a reduced frequency of CD27- IL-17-producing γδT cells in an allergy tolerance induction murine model mediated by pre conceptional immunization with OVA, similar to a previously published study." (PMID 34205753, 2021).
antibody deficiency (5 papers, 2014 to 2022). "In support of this view, antibody deficiency is also one of the main clinical features in CD27-deficient patients." (PMID 33996677, 2021). "Duodenal polyposis was diagnosed as being associated with IgA deficiency, IgM hypogammaglobulinemia and specific antibody deficiency, with a decrease in CD27‐positive B cells." (PMID 33363994, 2020). "Low frequencies of switched memory B cells (CD19+CD27+IgM−IgD−) have been associated with inflammatory/granulomatous and splenomegaly CVID clinical phenotypes, but the status of this B cell subset in those with secondary antibody deficiencies is unknown." (PMID 24971644, 2014). "Regarding B cell subsets, CD19-deficient patients show a normal number of mature peripheral B lymphocytes, decreased number of CD27+IgD+ and CD27+IgD- memory B cells, defective SHM and CSR, impaired antibody response following vaccination and hypogammaglobulinemia." (PMID 35784324, 2022).
B cell lymphopenia (5 papers, 2014 to 2022). "The patient presented B-cell lymphopenia and had low levels of memory B-cell subsets (CD27+, CD27+IgD+, and CD27+IgD−) for his age." (PMID 35338423, 2022). "B-cell lymphopenia was one of the initial observations in SLE patients and subsequent flow cytometry studies have shown decreased absolute numbers of both CD27+ and CD27− B cells." (PMID 25880288, 2015). "As with B cell lymphopenia in general, the numbers of naive (IgD+CD27–), non-switched memory (IgD+CD27+), and switched memory B cells (IgD–CD27+) were significantly lower in patients with a severe course." (PMID 32937615, 2020). "Abnormalities of the B cell compartment in WAS include B cell lymphopenia, reduced number of CD21/CD35-expressing B cells and of unswitched and switched CD27+ memory B cells, and an increased proportion of circulating CD19+ CD21low CD38low autoreactive-prone B cells." (PMID 25101082, 2014).
clear cell renal cell carcinoma (5 papers, 2021 to 2024). "And the expression of CD27 in the human renal clear cell cancer cell line (Caki-2) was significantly increased compared with the Human Kidney-2 cell line (HK-2)." (PMID 38169519, 2024).
colitis (5 papers, 2018 to 2026). Inflammation of the colon. "Evidence from two mouse models of colitis suggests that binding of CD27 to its ligand CD70 on antigen-presenting cells plays a role in mediating colitis." (PMID 34722568, 2021). "In the present study, we found increased mRNA expression of genes related to inflammatory and immune responses, including Cd27 and Cd40, as well as the chemotactic receptor Ccr8, in MLB cells from colitis rats." (PMID 40331987, 2025). "To verify whether MGP contributes to the therapeutic effect of MSCs in vivo, we established the experimental colitis mouse model with 2,4,6-trinitrobenzene sulfonic acid (TNBS), which shows symptoms similar to clinical CD27,28." (PMID 29880866, 2018).
colon cancer (5 papers, 2017 to 2025). "Compared with normal colon epithelial cells (NCM460), CD27 was highly expressed in three colon cancer cells lines, SW480, HCT116 and RKO." (PMID 38169519, 2024). "The study also revealed that “CD25hi CD45RA+ CD4 not Treg AC” was causally related to rectal cancer and colon cancer, and “CD27 on unsw mem” to rectal cancer and cancer of the small intestine." (PMID 38533503, 2024). "In contrast, CD27, CD276, LAG3, LGALS9, PDCD1, and TMIGD2 showed a highly enriched trend of expression with RFX1 in colon cancer." (PMID 41425715, 2025). "Although CASP7 was decreased in colon cancer as a consequence of gene deletion, no data was available for the CASP5 or CD27 genes, while BCL2 was over-expressed in cancer tissue." (PMID 28962550, 2017).